TNF (tumor necrosis factor)
Diseases named in the same sentence as TNF in open-access papers (continued):
Sharing a sentence is not in itself a finding about the gene and the disease.
lymphoma (continued). "In mice engrafted with CD19+ Raji lymphoma cells, those infused with CD19-directed CAR T-cells rapidly developed CRS, and administration of dasatinib significantly decreased levels of IFN-γ, GM-CSF, IL-2, and TNF-α and protected mice from fatal CRS." (PMID 33643299, 2020). "This study showed that different inflammatory factors such as lipopolysaccharide, 12-o-tetradecanoylphorbol-13-acetate, hydrogen peroxide, okadaic acid, and ceramide induced the production of IL-1b and TNF-α in human pulmonary epithelial cells (A-549), fibroblast (HFL1), and lymphoma cells." (PMID 31827685, 2019). "Cultures exposed to the polyclonal stimulus (PMA + ionomycin) showed that CD4+ T cells from HIV+ patients with lymphoma were not able to produce TNF-α, IFN-γ, and/or IL-2 (p < 0.05)." (PMID 30337929, 2018). "We monitored EBV load in RA patients under these treatments and found that long term usage of methotrexate or TNF inhibitors does not increase EBV load and is associated with reduced risk to develop lymphoma." (PMID 28199343, 2017). "Our results show that the LTA, but not the TNF gene, polymorphism serves as a genetic marker for NK/T-cell lymphoma, which suggests that subtle genetic differences may be involved in regulating different signaling pathways and leading to different pathogenesis among lymphoma subtypes." (PMID 26108796, 2015). "The same authors in a following work, during 89,710 person-years of followup of RA from 1998 to 2005, did not observe evidence for an increase in the incidence of lymphoma among patients who received anti-TNF therapy." (PMID 23133455, 2012). "And, identically, it has no repercussions on TNF-α induced cell death, despite that α-tocopherol has already been reported to protect U937 lymphoma cells form this kind of treatment, but for a short term period." (PMID 22590613, 2012). "Case reports of lymphoma associated or not with EBV, treated with anti-TNF drugs and regressing after withdrawal of therapy have also been reported." (PMID 19470150, 2009). "KEGG pathway analysis revealed that proteins upregulated in NR patients were enriched in cytokine-cytokine receptor interactions and TNF signal pathways in NSCLC, adherent junction and apoptosis in ASPS, and EGFR TKI resistance and complement coagulation cascades in lymphoma patients." (PMID 38349411, 2024). "The role of TNF- α antagonists in causing NMSC and lymphomas has not yet been defined." (PMID 39046819, 2024). "However, higher EBV load leads to lymphomas in immunosuppressed individuals and HIV patients by TNF-mediated polyclonal activation of B cells induced either directly by HIV-1 proteins or indirectly by immune activation through TLR-mediated recognition of translocated microbial products, etc." (PMID 38751600, 2024). "Regarding possible triggers, lymphoma-complicated CLS patients have elevated levels of various cytokines, such as granulocyte colony-stimulating factor (G-CSF), interleukin-6 (IL-6), interleukin-10 (IL-10), interferon-gamma (IFN-γ) and tumor necrosis factor alpha (TNF-α)." (PMID 39072323, 2024). "Meanwhile, in lymphoma, knocking down LSD1 in CD19-CAR T cells can also significantly improve the anti-tumor effect by maintaining the proliferation rate of CD19-CAR T cells, then promote their secretion of IFN-γ, tumor necrosis factor-α (TNF-α) and IL-2, and enhance cytotoxicity and lytic activity." (PMID 39629133, 2024). "The mean age at diagnosis of lymphoma was 47 ± 17 years old in those patients treated with anti-TNF before the diagnosis of lymphoma vs. 63 ± 12 years old in those patients not treated with anti-TNF (p = 0.01)." (PMID 36765708, 2023).
lymphoma (continued). "In a mouse model of lymphoma, a mutation preventing the PIDD/NEMO-dependent activation of NF-kB blocks the early IR-induced activation of NF-kB (4–24 h) and production of TNF-α (5–48 h) but not lymphoma, suggesting that activation of these inflammatory factors is not essential in this time period." (PMID 32399610, 2020). "MSCs isolated from spontaneous lymphomas have a strikingly high expression of CCL2 compared with bone marrow-derived MSCs (BM-MSCs), and promote tumor growth by recruiting type 2 like TAMs to tumor site, a phenomenon that can be mimicked by treating BM-MSCs with tumor necrosis factor alpha (TNF-α)." (PMID 25857315, 2015). "However, another report has indicated that patients receiving anti-TNF antibody therapy had a significantly higher incidence of lymphoma than patients without anti-TNF antibody therapy." (PMID 24721419, 2014). "Several of the studies that were included in our analysis presented odds ratios for lymphoma in RA patients who received anti-TNF therapy compared with RA patients who did not receive anti-TNF therapy, and none showed a statistically elevated risk associated with anti-TNF use." (PMID 18433475, 2008). "Therefore, it is also important to advise that in clinical practice, an important proportion of lymphomas could be diagnosed in those patients without previous treatment with immunosuppressive or anti-TNF drugs." (PMID 36765708, 2023). "In previous proof-of-concept work, we demonstrated that STAR2, a nonameric TNFR2-specific variant of mouse TNF, could not only safely expand Tregs in vivo but also protect allo-HCT recipients from acute GvHD while sparing anti-lymphoma and anti-infectious properties of transplanted allogeneic Tcons." (PMID 35769484, 2022). "Furthermore, the pro-inflammatory cytokines interferon-γ (IFN-γ), tumor necrosis factor-α (TNF-α), and interleukin-6 (IL-6) in HL and NHL patients were studied and compared to those of healthy controls to further understand the role of cytokines in the pathogenesis of lymphoma." (PMID 35692834, 2022). "In lymphoma isolated cells treated with RSV, irrespective of doses, whenever there was a decrease in one cytokine (e.g., TNF-α), there was an increase in the level of the other (e.g., IL-10) and vice versa." (PMID 35928372, 2022). "Further, NFκB inhibition did not result in altered expression of death ligands such as TNF, CD95L and TRAIL in lymphoma cells." (PMID 28233787, 2017). "In addition, necrotic cells obtained from mouse EL-4 (lymphoma) or WHEI 164 (fibrosarcoma) cell lines were unable to trigger CD40 expression or TNF (non-detectable values) in microglia." (PMID 18844999, 2008).
liver disease (261 papers, 1997 to 2026). "While exhibiting strong antiviral effects, TNF-α is also implicated in proinflammatory processes exacerbating the severity of liver disease upon HEV infection." (PMID 40175091, 2025). "Inflammation and elevated cytokines such as TNF-α and IL-1β are known to follow hepatocellular injury and are associated with the pathogenesis of liver diseases, in part, through the activation of the NF-κB signaling pathway." (PMID 37108064, 2023). "The cytokines most commonly associated with hepatic disorders are the pro-inflammatory cytokines TNF-α, IL-1, IL-6, and transforming growth factor (TGF)-β." (PMID 38007457, 2023). "Results of animal studies mimicking liver diseases of various etiologies have suggested that targeting TNFα release with specific antibodies is associated with decreased expressions of several cytokines including IL6." (PMID 37683301, 2023). "Overall, the pathogenic role of TNFα in other hepatic diseases such as non-alcoholic fatty liver disease or autoimmune liver disease is well-established." (PMID 37063909, 2023). "Induction of inflammation has been implicated in IR-mediated hepatic disease, which was confirmed by the upregulated gene expression levels of Bax and IL-1β as well as upregulated protein expression levels of TNF-α and IL-6 in the vehicle-treated IR rats." (PMID 36655319, 2023). "By revealing this novel role of Bcl-3 in regulating TNF-induced hepatic cell death, this study provides a potential therapeutic target for liver diseases caused by TNF-related apoptosis." (PMID 34853447, 2022). "TNF-induced cytotoxicity has been implicated in various liver diseases, including alcoholic liver disease and chronic viral hepatitis, as well as acute liver injury." (PMID 34853447, 2022). "Among the well-recognized mediators, TNF-α, IL-6, and Il1β have been implicated in the regulation of inflammation in liver diseases." (PMID 36588728, 2022). "From the perspective of liver disease such as non-alcoholic steatohepatitis, the inflammatory cytokines (IL-1β, IL-2, and TNF-α) are produced in the liver and are associated with disease (Bruscalupi, Agostinelli, Stronati & Cucchiara, 2015)." (PMID 34917853, 2021). "Inflammatory factors such as transforming growth factor-beta (TGF-β) and tumor necrosis factor (TNF) are key inflammatory regulators in the progress of the liver disease, which can cause or aggravate liver cell damage." (PMID 34262454, 2021). "TNFα, which is mainly produced by activated macrophages during inflammation, has been implicated as an important pathogenic mediator during liver diseases." (PMID 30185788, 2018). "Many studies also demonstrated that IL-1b and TNF-α play a key role in the development and maintenance of inflammatory and those cytokines' elevation is associated with many liver diseases." (PMID 26881046, 2016). "There is ample evidence of the central pathogenic role of TNF-α in development of a variety of liver disease modalities, particularly in mortality, acute liver injury, and fulminant hepatitis induced by D-GalN/LPS." (PMID 24799907, 2014). "Hepatocytes bear a variety of cytokine receptors and the inflammatory cytokines IL-6, IFN-γ and TNF-α play pathogenic roles in liver disease." (PMID 23403509, 2013). "In the present study in patients with ACLF, we observed elevated serum levels of five cytokines commonly associated with inflammatory liver disease (IL-6, IL-8, IL-10, TNF-α, and sTNF-αR1) at baseline." (PMID 17156425, 2006). "Therefore, the reduction in the TNF-α level can effectively block the inflammatory pathway associated with liver injury and inhibit the development of liver disease." (PMID 39861457, 2025). "Moreover, the TNF gene polymorphism is associated with liver disease, and two meta-analyses indicate the TNF-238 polymorphism is significantly associated with alcoholic liver disease and alcohol dependence/abuse." (PMID 39880903, 2025).
liver disease (continued). "TNF-α is associated with numerous phenotypes, including decreased pulmonary function, early infection of P. aeruginosa, decreased bone density, and an increase in liver disease development." (PMID 40225935, 2024). "Taken together, these findings highlight the role of pro-inflammatory monocytes in liver injury and also suggest that TNF+ monocytes may be a potential biomarker in predicting risk of liver disease in HBV/HDV co-infection." (PMID 37877022, 2023). "Furthermore, high levels of TNF-α in HBV infection have been associated with more severe liver disease symptoms." (PMID 36052277, 2022). "Therefore, we attempted to find new targets for liver diseases caused by TNF-induced hepatotoxicity." (PMID 34853447, 2022). "Taken together, these findings suggest that Bcl-3 could serve as a potential therapeutic target for liver diseases caused by TNF-induced apoptosis." (PMID 34853447, 2022). "TNF-α has been implicated as an important pathogenic mediator in a variety of liver diseases." (PMID 23653861, 2013). "Clotting factor deficiencies may also be due to reduced synthesis for hepatic disease, increased clearance in enlarged spleen, or accelerated consumption in a state of low-grade intravascular coagulation and fibrinolysis, supported by IL-1α, TNF-α, and IL-6." (PMID 36498496, 2022). "As immunity plays a pivotal role in the natural course of HBV, the outcome of the infection, and the pathogenesis of liver disease, the genes encoding inflammatory mediators (e.g., TNF-α, TGF-β, and IL-37) may be prospective candidates to predict the progression of HBV-mediated disease severity." (PMID 31073186, 2019). "In recent years, TNFR1-associated death domain protein (TRADD), a pivotal adaptor molecule in the TNF signaling pathway, has been found to play a dual regulatory role in the pathogenesis of liver diseases." (PMID 40565323, 2025). "There is evidence that TNF-alpha contributes to the development of inflammation and tissue damage in the setting of liver disease." (PMID 40225279, 2025). "The IL-17 signaling pathway indirectly triggers the release of proinflammatory cytokines, including TNF and IL-6, which subsequently activate the NF-κB pathway, thereby exacerbating inflammatory liver diseases and related pathological conditions." (PMID 40238193, 2025). "Of note, baseline expression of IFNγ and TNFα appeared to be similar in CD8+ T cells of patients across all stages of liver disease compared with healthy controls." (PMID 41028194, 2025). "GA can inhibit the release of serum tumor necrosis factor-α (TNF-α) induced by acetaminophen, which helps to slow down the progression of liver diseases." (PMID 40786042, 2025). "Apart from the direct inhibition of angiogenesis, thalidomide can reduce portal hypertension by inhibiting TNF-α synthesis and reducing nitric oxide production, blunting the development of hyperdynamic circulation." (PMID 41304934, 2025). "The MCD model shows a notable rise in pro-inflammatory cytokines like IL-1β and TNF-α in the intestines, suggesting a connection between gut inflammation and the advancement of liver disease." (PMID 41001122, 2025). "As reported by C. D’Melloand M.G. Swain (2011), cytokines TNF, IL-1β, and IL-6 arelikely to be key promoters of central neural alterations inchronic liver diseases." (PMID 40144377, 2025). "Its central role in TNF signaling and its ability to bridge cell death and immune-inflammatory responses provide a robust theoretical foundation for understanding liver disease mechanisms and developing targeted therapies." (PMID 40565323, 2025). "Current researches have demonstrated that TNF, IL-1α/β, IL-1Ra, IL-6, IL-18, IL-33, IL-36, IL38, CCL2 and CCR2 are closely associated with liver disorders." (PMID 41333471, 2025). "Elevated circulating levels of inflammatory cytokines, including interleukin IL-6, IL-1, and TNF-α, can be found in liver disease." (PMID 40430241, 2025).
liver disease (continued). "Liver disease is often accompanied by an inflammatory response, and inflammatory mediators such as TNF-alpha and IL-6 can affect lipid metabolism, leading to elevated lipid levels." (PMID 39678246, 2024). "Our findings suggest that the expression level of TNF-α in the liver of hepatic fibrotic rats was initially low, but FMGs restored its levels to normal, indicating a protective effect against liver disease by regulating the inflammatory response." (PMID 39195542, 2024). "The correlation between TNF-α and miR-122 in the liver appears multifaceted, as their interplay contributes to the pathogenesis of many liver diseases." (PMID 39666185, 2024). "miR-155 is highly expressed in total liver, hepatocytes, and KCs of a mice model of liver disease, and this upregulation contributes to TNF-α production." (PMID 39133714, 2024). "The interaction between microRNA and TNF-α represents a crucial dynamic in the progression of various liver diseases." (PMID 39666185, 2024). "TNF-α induces severe inflammatory response and hepatocyte apoptosis, therefore contributing to a variety of liver diseases." (PMID 38164484, 2024). "Systemic inflammatory markers such as C-reactive protein (CRP), lipopolysaccharide (LPS), interleukin-6 (IL-6), tumor necrosis factor-alpha (TNF-α), soluble CD14 (sCD14), soluble CD163 (sCD163), and D-dimer are linked to cardiovascular and liver diseases." (PMID 39529759, 2024). "RIPK1 kinase plays an important role in liver disease pathogenesis by regulating caspase-dependent hepatocyte apoptosis induced by TNFα." (PMID 37169760, 2023). "This pathway is subdued in unstressed healthy conditions but becomes activated at the time of KC expansion and TNF-α induction in steatotic liver disease models." (PMID 37937648, 2023). "Abnormal activation of the TNF signaling stimulates inflammation and apoptosis, which are intertwined during the development and progression of liver diseases." (PMID 36622102, 2023). "Consistent with the broad anti-inflammatory effects of C15:0 shown in our current study, daily oral C15:0 supplementation over 12 weeks lowers the proinflammatory cytokines MCP-1, IL-6, and TNFα, as well as IgG, in animal models of metabolic and liver disease." (PMID 37960259, 2023). "TNF-α plays a vital role in many stages of liver diseases as the degree of fibrosis develops via its mediated chronic inflammation." (PMID 36978885, 2023). "A similar study showed that the influence of IL17 with the synergetic role of TNFα contributes to the development of inflammatory liver diseases in primary hepatocytes." (PMID 37947641, 2023). "Here, we have found that a high level of TNF-α and IL1β in the serum of chronic alcoholic with either -238GA or -31CT genotype correlated well with their liver disease status." (PMID 38146363, 2023). "Tumor necrosis factor (TNF) signaling pathway is a classic inflammatory signaling pathway, which can promote the generation of many diseases, including liver diseases." (PMID 37035802, 2023). "TNF-α, IL-1β, IL-6, and IL-18 are often used as markers of inflammatory responses and are involved in the induction of liver diseases." (PMID 36865438, 2023). "Increasing evidence suggests that TNF-triggered pathways leading to hepatocyte death serve as attractive targets for therapeutic intervention in liver diseases." (PMID 34853447, 2022). "Clinical and experimental data demonstrated that expression of the TNF-α and IL-6 genes are increased and positively correlated with the severity of the liver disease in human and animal models." (PMID 35806336, 2022). "Tumor necrosis factor-α has various functions in liver disease, including attraction and activation of inflammatory cells as well as mediation of hepatotoxicity and regeneration." (PMID 34954190, 2022).